HP (haptoglobin)
Diseases named in the same sentence as HP in open-access papers (continued):
Sharing a sentence is not in itself a finding about the gene and the disease.
infection (continued). "The strong positive correlations between the transcripts of the CP and SAA3 genes and between those of the CP and HP genes in CLECs imply the combined action of their coded proteins against infection within these cells during chronic mastitis." (PMID 32867772, 2020). "Serum amyloid A (SAA), haptoglobin (HP), and ceruloplasmin (CP) were produced by liver and considered prognostic biomarkers for acute inflammation in dogs as a result of tissue infection or inflammation." (PMID 33363329, 2020). "Haptoglobin (Hp) is a moderate positive APP involved in host defense responses to infection and inflammation." (PMID 33260846, 2020). "With excess hemolysis caused both by transfusing longer-stored RBCs and bacteria producing hemolysins, the haptoglobin proteins during infection can become saturated and the reticuloendothelial system is unable to perform the normal function of clearing CFH." (PMID 38362479, 2020). "In our study, goats with CCPP showed significantly elevated HP levels compared with healthy goats demonstrating a strong APR to the MCCP infection." (PMID 33240679, 2020). "T4 antigen, the pilus backbone protein of M4 GAS, binds haptoglobin, an abundant human acute-phase protein upregulated upon infection and inflammation, on the bacterial surface." (PMID 32694142, 2020). "Previous studies for significant changes in acute phase proteins in mice showed that Serum amyloid P and haptoglobin increased in experimental infection with Trypanosoma." (PMID 32257894, 2019). "Specifically, the iron sequestration molecules haptoglobin and lipocalin-2 were >100-fold induced during infection." (PMID 31869388, 2019). "Overall, an increase in WBCs is generally delayed during an infection compared with acute phase proteins such as haptoglobin." (PMID 31649120, 2019). "Both ovotransferrin and haptoglobin increase with inflammation because they bind to and remove haem from circulation during infection, so that haem is unavailable as nutrient to pathogens (Horrocks, Irene Tieleman, & Matson, 2011)." (PMID 30659607, 2019). "Among the early response proteins in plasma, eight showed differential abundance as early as 6 h post-infection, and these included haptoglobin, Serpin A3-6, Serpin A3-8, vWF, LBP, sCD14, MBL1, and APOA4." (PMID 31803186, 2019). "We also found splits based on infection/infestation for haptoglobin, hemolysis, and neutrophil to lymphocyte ratio." (PMID 31766647, 2019). "Plasma concentrations of the acute phase protein haptoglobin in cattle have previously been reported to change from negligible levels to increases of 100 fold upon stimulation or infection and are therefore a good indicator of the health status of calves." (PMID 30719285, 2019). "Haptoglobin has a higher sensitivity for detecting disease when compared with other acute-phase proteins, due to it is more pronounced and prolonged response to infection." (PMID 30477479, 2018). "Haptoglobin is an acute-phase protein responsive to inflammation and infection that has already been shown to exert immune modulating functions on the innate and adaptive immune system of the pig." (PMID 29724161, 2018). "CD163 is involved in the cytokine response to infection and immune stimuli as well as hemoglobin-haptoglobin (Hb-Hp) uptake." (PMID 29925651, 2018). "Studies in the Democratic Republic of Congo (DRC), Cameroon, Cote D’Ivoire, Guinea and Uganda have found evidence for polymorphisms in HP, IL6 and APOL1 associated with outcome of infection." (PMID 29470556, 2018). "In bovine, however, haptoglobin is a major posAPP and its concentration in plasma is increased during inflammation, infection, and often during the transition period." (PMID 28781774, 2017). "In cattle, the increase in SAA and haptoglobin is expected to be major, and the increase in fibrinogen is likely to be moderate, following injury or infection." (PMID 28956843, 2017).
infection (continued). "Acute phase proteins (APPs) such as SAA, haptoglobin, and fibrinogen are synthesised in the liver in response to cytokines involved with inflammation and infection." (PMID 28956843, 2017). "Previous studies have shown that haptoglobin can increase or decrease depending on the type of infection." (PMID 28070333, 2017). "In ovine caseous lymphadenitis model, haptoglobin (1.65 ± 0.21 g/L) and serum amyloid A (18.1 ± 5.2 mg/L) concentrations peaked after 7 days post-injection, a point at which the acute infection became chronic." (PMID 26961495, 2016). "Haptoglobin contributes to protect host from microbicidal reaction elicited by infection, and our results showed its production in response to antigen challenge as reported in previous bird studies assessing this inflammatory marker." (PMID 28725417, 2016). "In particular, proteins participating in iron sequestration were up-regulated during infection, including ferritin, ceruloplasmin, lactoferrin, and haptoglobin." (PMID 27982111, 2016). "Haptoglobin is a major acute phase protein in the pig whose concentration in serum can vary in response to injury, infection, inflammation or stress." (PMID 26999224, 2016). "Following infection, haptoglobin levels in the haemopexin-null mice reached a peak at day 7 post infection with a median of 1324 ug/mL while the levels in both the haemopexin wild type and haemopexin heterozygous mice remained undetectable." (PMID 26691827, 2015). "Haptoglobin levels increase in patients with inflammation and infection, and this protein acts as a potent anti-inflammatory agent." (PMID 26388860, 2015). "Haptoglobin is an important acute-phase protein, which can assess the innate immune system’s systemic response to infection, inflammation, or trauma, including hemoglobin-binding capacity, in maintaining the iron homeostasis in cattle." (PMID 26202328, 2015). "After 12 weeks’ high-cholesterol diet on both groups and 2 weeks’ infection with CagA+ HP in Group A, we found significantly increased serum YKL-40 and CRP levels in the infected group." (PMID 23573226, 2013). "They concluded that HP-positive patients should therefore be treated for the infection, to elude a long-term significant increase of gastric and/or duodenal peptic disease subsequent to renal transplantation in these immune depressed subjects." (PMID 25340117, 2013). "Circulating concentrations of lymphotactin, MIP-1γ, MPO, MMP9, as well as VCAM-1, CRP, SAP, and haptoglobin were altered with Hb-infection and reduced in Hb-infected mice treated with anti-IL-7Rα M595." (PMID 23057802, 2012). "Previous studies have shown a correlation between increased serum levels of bovine haptoglobin (HP) and the onset of clinical disease in bovine respiratory disease, as well as in infections with bovine respiratory syncytial virus." (PMID 21592356, 2011). "Serum and casein-depleted milk cytokine levels (interleukin-8, interferon-γ, and transforming growth factor-β1), as well as serum haptoglobin concentrations were monitored over time after intramammary infection with each of the three S. aureus strains." (PMID 21884610, 2011). "Haptoglobin, an acute phase protein, is released by hepatocytes and mediate the inflammatory response to injury, trauma, or infection." (PMID 20646269, 2010). "For the Hampshire pigs a positive correlation was observed between clinical scores and the concentration of haptoglobin in plasma at 4 days after infection (r = 0.56; p < 0.01)." (PMID 19383119, 2009). "Positive correlations were found at 4 days post-infection between clinical scores and haptoglobin in plasma (r = 0.614; p < 0.001) for the same breed." (PMID 19383119, 2009). "The pre-infection plasma harvested from the Large White breed contained significantly higher levels of haptoglobin than plasma from the other three breeds." (PMID 19383119, 2009). "In our study the haptoglobin concentration in plasma at 4 days post-infection mirrored the clinical manifestations." (PMID 19383119, 2009).
infection (continued). "Haptoglobin concentration appears to plateau in the ML group from day 6 to 13, corresponding to the days when these calves were treated, potentially indicating the high infection rate." (PMID 39943212, 2025). "The lower haptoglobin concentration in pigs fed ZnO likely reflects the lower proportion of these pigs experiencing diarrhea, and therefore a smaller acute phase response to infection." (PMID 40411481, 2025). "It is possible that the haptoglobin concentrations may have been affected by instances of infection." (PMID 39943212, 2025). "Haptoglobin is a member of the acute-phase proteins, which are blood proteins primarily synthesised in the liver and released into blood usually after inflammation, damage, and infection." (PMID 40362043, 2025). "HP concentrations can increase in reactive states, such as infection and trauma." (PMID 39458532, 2024). "Haptoglobin, for example, is known to be elevated during infection as an acute phase reactant and might be able to counteract the potential effects of low-grade intravascular haemolysis." (PMID 39000133, 2024). "Similarly, the involvement of HP in “response to oxidative stress” and “response to reactive oxygen species” indicates its role in mitigating oxidative damage during infections, enhancing cellular resilience against viral onslaughts." (PMID 39456924, 2024). "However, across multiple studies, elevated haptoglobin levels have been found to be consistently indicative or predictive of BRD infection." (PMID 38662753, 2024). "However, haptoglobin levels can be influenced by various factors, including inflammation and infection." (PMID 39234172, 2024). "Haptoglobin is a highly conserved acute-phase protein that responds to infection and inflammation." (PMID 38535735, 2024). "Therefore, decreasing haptoglobin concentration with increasing urban cover cannot be solely interpreted as evidence of an impaired immune response to infection." (PMID 36353782, 2023). "Early after infection, IL-6 conducts the synthesis of acute phase proteins (including C-reactive protein (CRP), fibrinogen, serum amyloid protein, and haptoglobin, among others) in the liver, which orchestrate the systemic host immune response independently of the site where infection takes place." (PMID 37818368, 2023). "This suggests that in birds, discrepancies in the direction of haptoglobin change may depend on the type of infection." (PMID 35477136, 2022). "CD163 is a scavenger receptor for haptoglobin/hemoglobin complex, considering its scavenging properties, it is possible that its downregulation by S27 contributes to release of heme-derived iron to support pathogen growth and infection." (PMID 35387075, 2022). "infection may lead to hematological abnormalities and haptoglobin raising in apparently health hosts." (PMID 36006358, 2022). "It is worth noting that haptoglobin is an acute phase protein that, besides binding to haemoglobin, also acts as an antioxidant and antimicrobial agent, playing a relevant role in the host defence responses to infection and inflammation." (PMID 34451800, 2021). "Haptoglobin is recognized to play an important role in suppressing inflammatory responses since increased regulation of haptoglobin is stimulated by inflammatory responses such as infection and autoimmune reactions." (PMID 34018701, 2021). "In response to urbanisation, we predict that nestlings in poorer nutritional state will have reduced levels of complement activity and natural antibodies, while haptoglobin concentrations might correlate positively with ectoparasite infections." (PMID 34491450, 2021). "Interestingly, pre-FM treatment concentrations of haptoglobin, IL-6, and NEFAs were significantly different between infection outcome groups." (PMID 34073753, 2021). "Higher serum HP levels could be persuaded by tissue injury (pleuropneumonia in this study) following inflammation and/or infection." (PMID 33240679, 2020).
infection (continued). "Additionally, early FMD infection has been shown to generate substantial peaks in serum levels of acute phase proteins haptoglobin (HP) and serum amyloid A (SAA)." (PMID 32121072, 2020). "In our SMA model, infected rhesus macaques had lower levels of plasma haptoglobin compared to infected cynomolgus macaques on days 10 (50.5 ± 14.56 vs 114.6 ± 18.09 mg/dL; p = 0.03) and 11 (40.72 ± 13.1 mg/dL vs 98.95 ± 9.431 mg/dL; p = 0.01) post-infection." (PMID 31831787, 2019). "Here, the trypanosome haptoglobin-haemoglobin receptor (HpHbR) has been exploited as a route of uptake for an antibody-drug conjugate (ADC) that is completely effective against Trypanosoma brucei in the standard mouse model of infection." (PMID 31120889, 2019). "The conclusion that iron availability is important for Mtb during infection is also supported by the observation that high concentrations of transferrin, haptoglobin, and hemopexin are present in the necrotic centers of lung granulomas, the primary sites of infection in human TB patients." (PMID 31534126, 2019). "Haptoglobin expression levels are known to increase with inflammation and infection and these may involve immunogenic mechanisms that are aimed at reducing oxidative stress within the thyroid follicles." (PMID 29301248, 2018). "Still, haptoglobin, an acute phase protein, is correlated to the degree of severity of an infection and is considered a predictive marker of inflammation because it indicates inflammation earlier than the immune responses and the appearance of clinical symptoms." (PMID 29596432, 2018). "Increased expression of several acute-phase reactants, such as amyloid A proteins (Saa1, Saa2, Saa3), amyloid P component serum (Apcs), haptoglobin (Hp), hemopexin (Hpx) and orosomucoid 2 (Orm2), was observed only in CerS2-null mice after transfer of iNKT cells and infection with LCMV." (PMID 29163475, 2017). "Haptoglobin is likely to play an important role in suppressing inflammatory responses, as it binds free hemoglobin released from ruptured red cells, and its plasma level increases in response to inflammatory stimuli such as infection and autoimmune reaction." (PMID 28966798, 2017). "Finally, the general increase in the haptoglobin concentrations that occurred from the first to the second sampling period is probably attributable to an inflammatory status resulting from the infection, which results in the increased synthesis of haptoglobin." (PMID 28070333, 2017). "However, irrespective of the direction of the change, there is a general consensus that haptoglobin concentrations change significantly in response to an inflammatory stimulus such as infection, injury or malignancy." (PMID 28070333, 2017). "For example, haptoglobin may be important to protect against infection induced by parasites as suggested by the positive correlation we found between haptoglobin and ectoparasite density in the plumage." (PMID 26275171, 2015). "Haptoglobin’s appearance in panda milk at the onset of lactation may, therefore, be protective against infection of the restructuring mammary tissues." (PMID 26587250, 2015). "Haptoglobin shows pre-infection levels of 0·65 mg/ml or below in all animals." (PMID 24734294, 2014). "Haptoglobin, synthesized primarily by hepatocytes, is stimulated by infection or inflammation." (PMID 21297956, 2011). "Haptoglobin was also more highly expressed in the spleen of males prior to infection." (PMID 21338512, 2011). "The mean haptoglobin concentration was between 1 and 25 μg/ml for all groups before infection." (PMID 19948011, 2009). "The haptoglobin concentration in plasma increased significantly in the samples harvested from German Landrace, Pietrain and Large White, but not in those from Hampshire pigs from pre-infection to day 4 post-infection." (PMID 19383119, 2009). "Plasma haptoglobin levels mirrored the clinical manifestations at 4 days post-infection." (PMID 19383119, 2009).
infection (continued). "At 4 days post-infection a positive correlation was established between clinical scores and the production of NO by blood leukocytes (r = 0.69; p < 0.01) and also between clinical scores and the plasma concentration of haptoglobin (r = 0.61; p < 0.05)." (PMID 19383119, 2009). "This study confirmed the sensitivity of haptoglobin as infection indicator following bacterial infections and is in agreement with other studies that showed an increase in the porcine acute phase proteins including haptoglobin, following bacterial infections." (PMID 19383119, 2009). "Bb-HP strain lacks several plasmids including the linear virulence plasmid 25 (lp25) as determined by PCR (data not shown), and is unable to cause infection in borrelia-sensitive C3H/He mice (data not shown)." (PMID 17049082, 2006). "Haptoglobin is a major acute-phase proteins in cow to assess the health and inflammatory response of animals; it is released from hepatocytes in response to tissue injury or infection and acts as a potent antioxidant as well as a potent suppressor of lymphocyte function." (PMID 40357192, 2025). "Thus, changes to haptoglobin concentration following an infection may reflect the intensity of immune response or the magnitude of an immune challenge." (PMID 36353782, 2023). "The fact that both genera were negatively correlated with haptoglobin concentration and that high abundances of Weissella prior infection may predict the occurrence of a mild immune response suggests that these genera might be important in providing bats with protection against pathogens." (PMID 37114064, 2023). "Haptoglobin is an acute phase protein in humans and mice, and although its key role is to bind free haemoglobin following haemolysis to prevent oxidative damage, haptoglobin will also increase rapidly in response to infection and/or injury, exhibiting a range of immunomodulatory properties." (PMID 35448838, 2022). "Haptoglobin is a positive acute phase protein, meaning concentrations increase in response to infection, inflammation, or trauma, any of which could result from the mouthparts of a tick puncturing the skin of a host and the multiday feeding period that follows." (PMID 31766647, 2019). "Among the four NSMI that we tested, haptoglobin showed the strongest potential as a surveillance marker in African buffalo: concentrations quickly and consistently reached high levels in response to experimental infection, remaining elevated for almost a month." (PMID 29375568, 2017). "The concurrent analysis and significant correlations between expression of the porcine HP and TF and bacterial afuB and ompP4 peaking short time after bacterial colonization, reveals urgency for both organisms in the attempt of controlling the available iron at the site of infection." (PMID 26018580, 2015). "Plasma haptoglobin levels have been found to rise rapidly in mice infected with T. congolense and this increase was the most sensitive marker of infection, the very early decline in CD163 expression could cause a reduction in haptoglobin uptake and the observed increase in plasma concentration." (PMID 19365556, 2009). "In the other parts of the study, it was also seen that prebiotic groups generally did not cause a lower and in most cases caused a higher haptoglobin concentration after infection compared to the control group, with the notable exception of GOS where the trend was a lower level." (PMID 19948011, 2009). "Analysis of plasma taken from control and prothrombin-depleted mice on day 8 of infection revealed that prothrombin depletion results in increased lactate dehydrogenase (LDH) and reduced haptoglobin." (PMID 39820014, 2025). "Several genes such as CP, HP, and ORM1 are involved in the acute-phase response, indicating that a decrease in CEBPB can influence systemic responses to injury, infection, or other stress factors." (PMID 41002959, 2025).